EPCAM (epithelial cell adhesion molecule)
Diseases named in the same sentence as EPCAM in open-access papers (continued):
Sharing a sentence is not in itself a finding about the gene and the disease.
prostate carcinoma (continued). "Notably, epithelial cell adhesion molecule (EpCAM) was associated with prostate cancer metastasis and chemo‐ or radio‐resistance through the PI3K/AKT signaling." (PMID 34105305, 2021). "This suggests that EpCAM is associated with the metastatic potential of prostate cancer cells." (PMID 25636521, 2015). "Interestingly, PC3M cells, a highly metastatic clone of PC3, express much higher levels of EpCAM than PC3, which suggests that EpCAM expression is associated with the proliferation and metastasis of prostate cancer cells." (PMID 25636521, 2015). "In the case of prostate cancer, overexpressed EpCAM associated with progression and distant metastasis, whereas increased 10-year survival rate of gastric cancer patients was confirmed to correlate with the increased EpCAM." (PMID 26718583, 2015). "Thus, the loss of EpCAM expression may explain the low CTC number in some patients with metastatic breast or prostate cancer, among other tumour types." (PMID 27711186, 2016). "Following TGF-β treatment of prostate cancer LNCaP cells, they observed that the ratios of EpCAM to prostate-specific membrane antigen (PSMA) changed from 4-fold to 0.5-fold, suggesting the initiation of EMT transition." (PMID 39926198, 2025). "EpCAM is frequently overexpressed in prostate cancer tissues compared to benign tissues and healthy controls." (PMID 40607417, 2025). "The presence of either or both EpCAM+ and PSMA+ CTCs underscores the underlying degree of tumor heterogeneity in prostate cancer and the need for multiple markers." (PMID 40672470, 2025). "PSCA, PSMA, and EpCAM are currently target antigens for research in prostate cancer using CAR T cell approaches." (PMID 40607417, 2025). "Using EpCAM-targeting CAR T cells generated from peripheral blood T cells of prostate cancer patients improves OS." (PMID 40607417, 2025). "It reduces tumor size in PC3 (low EpCAM expression) and PC3M (high EpCAM expression)-induced prostate cancer mouse models." (PMID 40607417, 2025). "Patient samples were subjected to staining for prostate-specific membrane antigen (PSMA) and EpCAM proteins, commonly expressed on the surface of prostate cancer cells and epithelial cells, respectively." (PMID 40671945, 2025). "In vitro studies demonstrated higher cytotoxicity against EpCAM-positive human prostate cancer cells (PC-3) compared to EpCAM-negative CHO cells, indicating selective targeting." (PMID 40869241, 2025). "In prostate cancer cells, EpCAM has tumor initiation potential and is involved in proliferation, invasion, metastasis and chemo/radiosensitivity via the activation of PI3K/Akt/mTOR signaling pathway." (PMID 40017594, 2025). "To test this concept, we assessed the immunostimulatory effects of XmAb808 combined with an EpCAM×CD3 bispecific antibody in cocultures of T cells with B7-H3+ EpCAM+ 22Rv1 human prostate carcinoma cells." (PMID 39301613, 2025). "Previous studies have demonstrated that EpCAM knockdown results in increased sensitivity to chemotherapy and radiotherapy in prostate cancer cells, which is interpreted by inactivation of PI3K/AKT/mTOR signaling." (PMID 38791091, 2024). "Castration-resistant prostate cancer CTCs were found primarily in the low EpCAM regions of the device." (PMID 38607014, 2024). "Previous studies have indicated notable clinical relevance associated with microseminoprotein-beta (MSMB) and epithelial cell adhesion molecule (EPCAM) for prostate cancer." (PMID 39443867, 2024). "CellSearch, an immunoaffinity-based CTC separation system using the EpCAM antibody, is approved by the U.S. Food and Drug Administration for breast, colon, and prostate cancer." (PMID 39001472, 2024). "Consistent with current results, EpCAM(+) CTCs reportedly correlate with a poor outcome in patients with metastatic non-small cell lung cancer, prostate cancer, and HCC." (PMID 39108869, 2024).
prostate carcinoma (continued). "Our findings showed that EpCAM antibodies were more effective in isolating CTCs from localized prostate cancer, whereas vimentin antibodies were more effective in advanced prostate cancer." (PMID 37345161, 2023). "For example, the CellSearch system approved by the Food and Drug Administration for CTCs detection in the identification of metastatic breast cancer, prostate cancer and colon cancer is based on the EpCAM expression." (PMID 36633681, 2023). "We have compared the expression of the often targeted EpCAM antigen in CTCs derived from prostate cancer patients with the EpCAM expression of several well-known cell lines using quantitative flow cytometry." (PMID 37055551, 2023). "Using this sensor, the authors reported that prostate cancer patients showed significantly higher levels of EpCAM and PSMA-positive exosomes, suggesting a good potential for diagnosis of prostate cancer." (PMID 36770486, 2023). "Prostate cancer spheroids vastly co-express stemness (CD44v9+ EpCAM+ CD133+ ESRP1/2+), epithelial (E-cadherin+), and mesenchymal (Vimentin+) markers, and markedly release EpCAM+ CD9+ EVs." (PMID 36671802, 2023). "Results show CTCs derived from castration-sensitive prostate cancer patients have varying but relatively low EpCAM expression, with median expression per patient ranging from 35 to 89,534 (mean 24,993) molecules per cell." (PMID 37055551, 2023). "In a sixth study, using near‐infrared dyes and EpCAM immunostaining, up to 439 CTCs per mL of blood (mean: 25 CTCs/mL; median: 10 CTCs/mL) were observed in a cohort of patients with localized prostate cancer." (PMID 36718027, 2023). "For EpCAM, we show an expression on CTCs that differs between castration sensitive prostate cancer patients, but is much lower than many of the cell lines often used to evaluate CTC enrichment technologies." (PMID 37055551, 2023). "The values derived with the EpCAM-based bead system are comparable to those CTC counts which have been isolated from patients with prostate cancer (mean 124 ± 400) using the FDA-approved EpCAM mAb-based CELLSEARCH® system." (PMID 37626772, 2023). "The blood samples of mice containing prostate cancer cells were mixed with EpCAM antibody-modified MNPs and were analysed using the MagRC device." (PMID 35448280, 2022). "EpCAM+ leukemia and prostate cancer cells exhibited increased resistance to chemotherapies, and knocking down EpCAM sensitized the chemotherapeutic agent-induced cell apoptosis." (PMID 36369033, 2022). "Some studies suggest that EpCAM can be used as a predictor of prostate cancer; it has an important activity in CaP proliferation, invasion, metastasis, and chemo-/radio-resistance associated with the activation of the PI3K/Akt/mTOR signaling pathway." (PMID 35205714, 2022). "Knockdown of EpCAM in prostate cancer cell lines inactivated the PI3K/AKT/mTOR signaling pathway, thus sensitizing the cancer cells to chemo/radio-therapy." (PMID 36369033, 2022). "Ni and colleagues utilised shRNA to knock down EpCAM expression in prostate cancer cell line PC-3 xenografts." (PMID 35158771, 2022). "A study revealed that serum-derived microsomes/exosomes in prostate cancer showed a four- to fivefold increase in the expression levels of EpCAM compared to healthy controls." (PMID 36369033, 2022). "Hybrid EMT was identified by the co-expression of epithelial (EpCAM+) and mesenchymal (Vim+) marker genes in an autochthonous murine prostate cancer model." (PMID 36552758, 2022). "We tested the feasibility of this using 3 prostate cancer CTC samples that were first enriched for EpCAM-positive cells." (PMID 35272673, 2022). "An in vivo study also showed that knockdown of EpCAM in a prostate cancer cell line prior to engraftment into mouse models led to increased radiosensitivity and prolonged survival of the tumor-bearing animals." (PMID 35992826, 2022).
prostate carcinoma (continued). "There is an overall paucity of preclinical studies specifically examining the effect of EpCAM adoptive treatment on prostate cancer cells, so further data are required." (PMID 35158771, 2022). "Consistently, hybrid EMT of prostate cancer cells within a tumor organoid (tumoroid) was identified by the co-expression of epithelial (E-cadherin+ EpCAM+) and mesenchymal (Vimentin+) markers with enhanced stemness." (PMID 36552758, 2022). "The epithelial cell adhesion molecule (EpCAM) is intensively overexpressed in 40–60% of prostate cancer (PCa) cases and can be used as a target for the delivery of drugs and toxins." (PMID 34298801, 2021). "A large retrospective study using tissue microarrays showed that high level of EpCAM expression was found in 94.1% of patients with lung, colon, and prostate cancers and observed a significant reverse correlation between EpCAM expression and survival time." (PMID 34922633, 2021). "The non-residualizing [125I]I-HPEM label provided the highest tumor-to-muscle and tumor-to-bone ratios 3 h p.i. and is the most suitable for imaging of EpCAM in the early stages of prostate cancer." (PMID 34298801, 2021). "Overall, the use of the radioiodine label in combination with the HPEM linker at the C-terminus was the most favorable for visualization of EpCAM expression in prostate cancer." (PMID 34298801, 2021). "Binding specificity of radiolabeled Ec1 variants to EpCAM-expressing PC-3 and DU145 prostate cancer cells was studied by saturating the EpCAM receptors with a large excess of unlabeled Ec1." (PMID 34298801, 2021). "A near-infrared dye DiD (1,1-dioctadecyl-3,3,3,3-tetramethylindodicarbocyanine) was used to label NK-92 cells and NK-92-scFv(MOC31)-zeta cells functionalized to target the epithelial cell adhesion molecule (EpCAM) antigen on prostate cancer cells." (PMID 33537909, 2021). "CAR-T cells were developed to target CSC-antigen EpCAM to eliminate prostate cancer, demonstrating that EpCAM-specific CAR-T cells have therapeutic potential for cancer treatment." (PMID 34946546, 2021). "CAR NK-92 cells expressing EpCAM accumulate in prostate tumor and are highly cytotoxic against EpCAM+ prostate cancer cells even at low doses." (PMID 33287875, 2020). "Other researchers investigated the migration of NK-92-scFv(MOC31)-zeta cells to EpCAM-positive prostate cancers in a rat model using MRI." (PMID 32455886, 2020). "It is important to remark on the presence in this list of KLK3 (PSA) as the broadly accepted prostate cancer marker and EpCAM, the molecule used for the isolation of CTCs in our approach and the one classically used for CTC isolation in carcinomas." (PMID 32630240, 2020). "The tumors from the spontaneous mouse prostate cancer model also showed the existence of three sub-populations: epithelial (EpCAM+Vim–), hybrid E/M (EpCAM+Vim+), and mesenchymal (EpCAM–Vim+)." (PMID 32143517, 2020). "EpCAM is a cell membrane glycoprotein highly expressed in primary and metastatic prostate cancer as compared to normal and benign hyperplastic prostates and is also considered as a CSC biomarker for multiple cancer types." (PMID 32183880, 2020). "Epithelial cell adhesion molecule (EpCAM) expression has been reported in many types of cancer, including prostate cancer (PCa)." (PMID 31324239, 2019). "In prostate cancer, miRNA200c and miRNA205 were shown to induce expression of EPCAM mRNA and protein." (PMID 31225512, 2019). "After normalization, 6–7 fold higher expression of EpCAM was seen with the EVs of less aggressive prostate cancer cell line LNCaP compared to more aggressive DU145 and PC3 cell lines." (PMID 31296879, 2019). "In a study in 2015, EpCAM-redirected CAR T cells were employed against EpCAM+ prostate cancer in both in vitro and in vivo models." (PMID 30108584, 2018). "T cells expressing second-generation EpCAM-specific CARs with the intracellular signaling domain of CD28 were reported to treat prostate cancers in mouse models." (PMID 30410941, 2018).
prostate carcinoma (continued). "Enumeration of EpCAM positive CTCs from peripheral blood samples was performed using CellSearch system, as a well-accepted strategy for prostate carcinomas." (PMID 28903376, 2017). "For example, EpCAM-specific CAR-expressing human peripheral blood lymphocytes inhibited tumor growth in an EpCAM+ prostate cancer metastasis mouse model." (PMID 28137313, 2017). "Using a prostate cancer, EpCAM+ PC-3 xenograft model, we first confirmed that EpCAM-targeted PLGA particles localized within the tumour 3 h post injection using in vivo fluorescence imaging." (PMID 28317839, 2017). "The widely used and FDA-approved CellSearchTM system is based on EpCAM positivity and multiple studies have demonstrated that the numbers of circulating EpCAM+ cells increased with prostate cancer progression." (PMID 28690641, 2017). "EpCAM was significantly overexpressed in metastasized prostate carcinoma compared with benign prostate hyperplasia, which served as a normal control." (PMID 27690012, 2016). "There are several studies that show a significantly elevated expression of EpCAM in prostatic carcinoma compared with benign prostate epithelium." (PMID 27690012, 2016). "Prostate cancer cells expressed low or moderate levels of cytokeratin and high levels of EpCAM in vitro, while levels of both were low in the leukemia lines." (PMID 27172799, 2016). "Next, EpCAM expression was seen in 82.3% of salvage prostatectomy specimens taken from patients with locally recurrent prostate carcinoma after external beam radiotherapy or brachytherapy." (PMID 27690012, 2016). "In the current study, EpCAM was expressed in 100% of prostate carcinoma lymph node metastases and 95% of prostate carcinoma bone metastases." (PMID 27690012, 2016). "Epithelial cell adhesion molecule (EpCAM) is a membranous protein of interest as an imaging target since it is overexpressed in prostatic carcinoma compared with benign prostate epithelium and compared with stroma." (PMID 27690012, 2016). "Absent EpCAM expression in normal lymph nodes and normal bone supports the use of EpCAM as a target with high specificity for prostate carcinoma." (PMID 27690012, 2016). "The current study evaluates the expression of EpCAM in prostate carcinoma lymph nodes, in matched normal lymph nodes, in prostate carcinoma bone metastases, and in normal bone by immunohistochemistry." (PMID 27690012, 2016). "Based on these results, EpCAM would be an attractive specific target for imaging purposes in prostate carcinoma." (PMID 27690012, 2016). "In conclusion, the purpose of the current study was to establish the feasibility of EpCAM as an imaging target for prostate carcinoma lymph node and bone metastases." (PMID 27690012, 2016). "First, we used flow cytometry to evaluate the basal levels of cytokeratin and EpCAM on the surface of human prostate cancer cell lines (PC3, DU145, LNCaP, and C4- 2B), with leukemia cell lines (RCH-ACV, 697, Nalm6 and RS4;11) as controls." (PMID 27172799, 2016). "In this study, we constructed a CAR targeting the cancer stem cell marker EpCAM and demonstrated that human PBLs transduced with the EpCAM-specific CAR can kill the prostate cancer cells PC3M and PC3, both in vitro and in vivo." (PMID 25636521, 2015). "PC3 cells were firstly used to test the existence of EMT in prostate cancer cells by EpCAM, CK and Vimentin immunostaining." (PMID 26397728, 2015). "Our data demonstrate that PBLs expressing with EpCAM-specific CARs have significant anti-tumor activity against prostate cancer." (PMID 25636521, 2015). "We show that EpCAM and integrin β4 are involved in migration, while uPA is involved in migration and invasion of metastatic prostate cancer cells." (PMID 24885350, 2014). "This is the first experimental evidence that as few as 50 EpCAM-positive prostate cancer CTCs putatively contain metastasis-initiating-cells (MIC)." (PMID 25593983, 2014).
prostate carcinoma (continued). "In human prostate cancer, several tissue studies have shown upregulated EpCAM in the tumor epithelium and in metastatic lesions." (PMID 24885350, 2014). "This is the first report showing that even as few as 50 EpCAM-positive live CTCs from metastatic prostate cancer patients can survive and grow in a xenograft assay, putatively containing metastasis-initiating-cells (MIC)." (PMID 25593983, 2014). "Recent increasing evidence suggests that EpCAM plays an important role in prostate cancer cell proliferation, invasion, metastasis and chemo/radio resistance associated with the activation of the PI3K/Akt/mTOR signaling pathway." (PMID 25019346, 2014). "EPCAM overexpression was observed in esophageal cancer, pancreatic cancer and ampullary cancer samples, colon cancers, gastric cancers, prostate cancers, and lung cancers." (PMID 24422715, 2013). "Anti-human EpCAM MBs efficiently bound to prostate cancer GFP-PC3 cells, lung adenocarcinoma A549 cells, and pancreatic adenocarcinoma BxPC-3 and ASPC-1 cells but did not appreciably bind to non-epithelial lymphoma JeKo-1 cells." (PMID 23516425, 2013). "Other studies also reported detection of CTCs in early stage prostate cancer using anti-EpCAM magnetic beads combined with PCR." (PMID 20598135, 2010). "As few as five prostate cancer cells were detected per 5 mL of whole blood in model system experiments using anti-EpCAM magnetic particles alone or in combination with anti-PSMA magnetic particles." (PMID 20598135, 2010). "Indeed, a large variation in EpCAM expression has been reported in CTC isolated from patients with prostate cancer, with differences observed both between patients and within individual patients." (PMID 41301007, 2025). "EpCAM expression has been established in various normal epithelial tissues and cancers, with its overexpression being particularly observed in colorectal, gastric, ovarian, and prostate cancers." (PMID 38627681, 2024). "MSMB and EPCAM could be prostate cancer-relevant indicators or contributors in various medical and pathological conditions, underscoring the importance of further exploration and validation." (PMID 39443867, 2024). "Adoptive transfer of peripheral blood lymphocytes (PBL) transduced with an EpCAM-specific CAR prevented metastasis of prostate cancer PC3 cells and significantly reduced tumor growth of PC3M cells in nonobese diabetic/severe combined immunodeficiency (NOD/SCID) mice." (PMID 38612911, 2024). "EpCAM is a type I glycosylated membrane protein expressed at low levels in a variety of human epithelial tissues, but overexpressed in most solid cancers, including prostate cancer and most of the studies reported to date use EpCAM as the target marker to identify potential CTCs." (PMID 39441869, 2024). "EpCAM-positive CTCs with a mesenchymal phenotype are more invasive than EpCAM-negative mesenchymal CTCs in mouse models of both metastatic breast cancer and prostate cancer." (PMID 38791091, 2024). "Similarly, adecatumumab delayed disease progression in prostate cancer patients with EpCAM+ tumors and rising prostate-specific antigen (PSA) levels after prostatectomy." (PMID 38612911, 2024). "Moreover, in prostate cancer, miR-200c and miR-205 have been shown to induce the expression of EpCAM mRNA and protein." (PMID 37375854, 2023). "However, even if the expression of EpCAM in prostate cancer is variable, one clinical trial evaluating the safety and efficacy of EpCAM CAR-T cells in patients with EpCAM-positive cancer is ongoing (NCT03013712)." (PMID 36831396, 2023). "Therefore, the merits and demerits of EPCAM as a target for CAR-T therapy in prostate cancer need further confirmation." (PMID 35205714, 2022). "Over-expression of EpCAM has been detected in colon, breast, lung, intestine, and prostate cancers." (PMID 36428553, 2022). "Interestingly, knockdown of EpCAM using siRNA in several prostate cancer cells has been shown to increase sensitivity to both chemotherapy and radiation." (PMID 35992826, 2022).